SLC16A2 (solute carrier family 16 member 2)
Diseases named in the same sentence as SLC16A2 in open-access papers:
SLC16A2 is named in the same sentence as 80 diseases in open-access papers, as found by Europe PMC text mining. Sharing a sentence is not in itself a finding about the gene and the disease. The quoted sentences say what the papers report.
Allan-Herndon-Dudley syndrome (58 papers, 2010 to 2026). "Pathogenic variants in SLC16A2 (the gene encoding MCT8) cause MCT8 deficiency (Allan-Herndon-Dudley syndrome, AHDS)." (PMID 40420837, 2025). "SLC16A2, a thyroid hormone transporter associated with Allan-Herndon-Dudley syndrome (OMIM# 300523), showed highest expression in early life (Dunn’s P value = 0.0041) and exhibited a sequential reduction with age." (PMID 41449219, 2025). "Allan-Herndon-Dudley syndrome (AHDS) is an X-linked disorder caused by pathogenic variants in the SLC16A2 gene." (PMID 40033291, 2025). "Pathogenic variants in SLC16A2 cause MCT8 deficiency (Allan-Herndon-Dudley syndrome), characterized by intellectual and motor disability and abnormal thyroid function tests." (PMID 40420837, 2025). "Inactivating mutations in the SLC16A2 gene, which encodes for MCT8, result in a rare X-linked disorder called Allan-Herndon-Dudley Syndrome (AHDS) or MCT8 deficiency." (PMID 37924081, 2023). "Mutations in SLC16A2 are the cause of Allan-Herndon-Dudley syndrome, associated with impaired thyroid metabolism, presenting with neurodevelopmental delay, hypertonia, and muscle weakness." (PMID 36978128, 2023). "Inactivating mutations in the MCT8 gene (SLC16A2) cause the Allan-Herndon-Dudley Syndrome (AHDS) or MCT8 deficiency, a rare X-linked disease characterized by delayed neurodevelopment and severe psychomotor disorders." (PMID 37924081, 2023). "Allan-Herndon-Dudley syndrome (AHDS) is an X-linked recessive neurodegenerative disorder caused by mutations in the SLC16A2 gene that encodes thyroid hormone transporter." (PMID 35382784, 2022). "Allan-Herndon-Dudley syndrome (AHDS) is an X-linked condition caused by pathogenic variants in the thyroid hormone transporter monocarboxylate transporter 8 (MCT8) gene SLC16A2." (PMID 33585976, 2021). "SLC16A2 (encodes for MCT8) inactivating mutation in humans can lead to Allan-Herndon Dudley-syndrome, a X-linked psychomotor and growth retardation." (PMID 32636400, 2020). "MCT8 is encoded by the SLC16A2 gene and the mutations that cause the inactivation of this transporter result in a rare X-linked disease known as Allan-Herndon-Dudley Syndrome (AHDS or MCT8 deficiency)." (PMID 32410949, 2020). "Studies of Allan-Herndon-Dudley syndrome and of mice with Slc16a2 mutations have established a requirement for Slc16a2 for T3 action in the brain and pituitary-thyroid axis but less is known about Slc16a10." (PMID 29535325, 2018). "These variants were believed to be involved in Allan-Herndon-Dudley syndrome, showing that SLC16A2 has its crucial function in other processes as well." (PMID 26015273, 2015). "Monocarboxylate transporter 8 (MCT8) deficiency, also known as Allan-Herndon-Dudley syndrome, is a rare, severely debilitating, and life-limiting genetic disorder caused by variants in the SLC16A2 gene that render the MCT8 thyroid hormone transporter partially or completely dysfunctional." (PMID 41508830, 2026). "Its role in TH transport is crucial for brain TH availability, evidenced by the devastating neurological impairments of Allan-Herndon-Dudley-Syndrome (AHDS) patients with mutations in the MCT8-encoding solute carrier family member 16a2 (Slc16a2) gene on the X-chromosome." (PMID 41310287, 2025). "The necessity for proteins that transport hormone across the plasma membrane of cells was indicated by finding mutations in solute carrier SLC16A2 (monocarboxylate transporter 8, MCT8) in Allan-Herndon-Dudley syndrome, an X-linked disorder of psychomotor and speech retardation." (PMID 29535325, 2018). "A second transmembrane transporter defect was found in the thyroid hormone (T3/T4) transporter SLC16A2, in a patient with Allan-Herndon Dudley syndrome, which resulted in a CII and CIV deficiency, where triiodothyronine (T3) has been suggested as an important regulator of mitochondrial activity." (PMID 30369941, 2018).
Allan-Herndon-Dudley syndrome (continued). "MCT8 deficiency (also known as Allan-Herndon-Dudley Syndrome or AHDS), caused by mutations in the MCT8-encoding gene SLC16A2 on chromosome Xq13.2, is a rare disorder consisting of severe intellectual and motor disability and abnormal thyroid function tests." (PMID 34679181, 2022). "The critical role of MCT8 within humans was recognized retrospectively by identifying mutations of the SLC16A2 gene (that encodes MCT8) producing the phenotype of severe psychomotor retardation, defined as Allan-Herndon-Dudley syndrome (AHDS)." (PMID 31182964, 2019). "990_991insGCTGC) were identified in SLC16A2, a gene that has been linked to Allan-Herndon-Dudley syndrome (AHDS)." (PMID 24721225, 2014). "The monocarboxylate transporter 8 (SLC16A2, MCT8) is the main TH transporter present in the brain during embryonic development, and mutations in this transporter lead to a rare and debilitating human condition known as the Allan-Herndon-Dudley Syndrome (AHDS)." (PMID 40593336, 2025). "Mutations in TH transporters like MCT8 (SLC16A2), and OATP1C1 (SLCO1C1) cause juvenile neurodegeneration and brain developmental disease, Allan-Herndon-Dudley syndrome. oatp1c1 (slco1c1) knockout zebrafish also showed a similar phenotype." (PMID 33685490, 2021). "Allan-Herndon-Dudley syndrome is a rare disease caused by inactivating mutations in the SLC16A2 gene, which encodes the monocarboxylate transporter 8 (MCT8), a transmembrane transporter specific for thyroid hormones (T3 and T4)." (PMID 32410949, 2020). "The importance of the TH-specific membrane transporter MCT8 (SLC16A2) for neurodevelopment in humans was revealed by the severe global neurological impairments identified in subjects with X-linked Allan-Herndon-Dudley syndrome (AHDS)." (PMID 29192226, 2017). "Mutations of the specific thyroid hormone transporter, MCT8 (Monocarboxylate Transporter 8, SLC16A2) cause an X-linked syndrome of profound neurological impairment and altered thyroid function known as the Allan-Herndon-Dudley syndrome." (PMID 24819605, 2014). "It is noteworthy that inactivating mutations in SLC16A2 produce a severe X-linked syndrome (Allan-Herndon-Dudley syndrome) with a lack of TH in target brain regions and excess TH in the peripheral tissues." (PMID 34671932, 2022). "Allan-Herndon-Dudley syndrome (AHDS; OMIM #300523), also known as monocarboxylate transporter 8 (MCT8) deficiency, is an X-linked disorder caused by pathogenic variants in the solute carrier family 16 member 2 (SLC16A2) gene." (PMID 40033291, 2025).
hypothyroidism (29 papers, 2013 to 2025). Abnormally low levels of thyroid hormone. "TH transporters seem to play a critical role in T3 signaling as showcased by the profound brain hypothyroidism observed in boys carrying mutations in the monocarboxylate transporter 8 (MCT8, SlC16A2)." (PMID 37204837, 2023). "Recently, some genes, such as TH transporters (Slc16a2) and DIOs D1, D2, and D3, were targeted to generate zebrafish hypothyroidism models for peripheral TH functional studies." (PMID 34440752, 2021). "Conditions known to interfere with normal neurodevelopment by compromising TH action include iodine deficiency, maternal and fetal hypothyroidism or hypothyroxinemia, and mutations of the nuclear TH receptor (TR) alpha and beta as well as of monocarboxylate 8 transporter (MCT8) gene SLC16A2." (PMID 31513589, 2019).
developmental delay (13 papers, 2014 to 2025). "Similarly, panels developed to screen for developmental delay or thyroid hormone-related disorders should include SLC16A2 so a diagnosis of MCT8 deficiency is possible." (PMID 39132310, 2024). "Patients with mutations in the monocarboxylate transporter 8 (MCT8, SLC16A2) suffer from X‐linked recessive Allan‐Herndon‐Dudley syndrome (AHDS), which is characterized by developmental delay and a severe movement disorder." (PMID 40088079, 2025). "Mutations in the MCT8 gene (SLC16A2) and in the OATP1C1 gene (SLCO1C1) can cause a psychomotor developmental delay in humans." (PMID 37298594, 2023). "MCT8 deficiency due to SLC16A2 variant causes AHDS characterized by mental and motor developmental delay, and thyroid functional abnormalities of high serum T3, reduced T4, and normal or mildly increased Thyroid stimulating hormone (TSH)." (PMID 35382784, 2022). "Finally, PKD has also been reported in association with mutations in the acetylcholine receptor gene CHRNA4 (in association with epilepsy and developmental delay), and in the thyroid hormone transporter SLC16A2 (also known as MCT8)." (PMID 33833732, 2021). "This case report further underscores the importance of including SLC16A2 in genetic screening panels for patients with nonspecific developmental delay and myelination abnormalities, even in the absence of elevated T3." (PMID 41438913, 2025).
Intellectual disability (8 papers, 2011 to 2023). "SLC16A2 gene mutations, encoding the thyroid hormone (TH) transporter MCT8, result in intellectual disability due to impaired TH uptake in the developing brain." (PMID 32477268, 2020).
thyroid (7 papers, 2021 to 2025). "To further substantiate that the observed clinical features are related to the identified variants in SLC16A2, we compared the serum thyroid function tests of the female index patients to those available from (self-reported) asymptomatic carriers and noncarriers." (PMID 40420837, 2025). "Next, we tested the percentiles for the fT3/fT4 ratio for their discriminatory power between pathologies that are either thyroid-related (e.g., in patients with mutations in THRA, SLC16A2, or SECISBP2) or not (e.g., in patients with cerebral palsy)." (PMID 39201272, 2024).
Dystonia (6 papers, 2014 to 2024). An abnormally increased muscular tone that causes fixed abnormal postures. "In this study, two novel pathogenic variants in the SLC16A2 gene were identified in two Chinese patients who exhibited symptoms of neurodevelopmental delay, extrapyramidal (dystonia, chorea and tardive dyskinesia), and pyramidal (spasticity)." (PMID 36458135, 2022). "We herein report a case involving a patient with MCT8 deficiency with a novel frameshift variant of SLC16A2 who presented with dystonia and cerebral hemisphere atrophy from early infancy." (PMID 33594047, 2021).
Graves disease (3 papers, 2021 to 2025). Graves' disease is an autoimmune disorder that leads to overactivity of the thyroid gland (hyperthyroidism).It is caused by an abnormal immune system response that causes the thyroid gland to produce too much thyroid hormones. "Two of these—Cxcl12 and Slc16a2—are particularly noteworthy because of potential links to the pathogenesis of Graves disease, in which inflammation and adipogenesis are selectively observed in retrobulbar fat, but not other adipose tissues." (PMID 33542375, 2021).
X-linked disease (3 papers, 2021 to 2023). X-linked form of disease. "Among these carriers, MCT8 seems to be specific for TH transport, and indeed mutations in the gene that encodes it (SLC16A2) cause a very rare X-linked disease known as Allan–Herndon–Dudley syndrome (AHDS) or MCT8 deficiency." (PMID 34070729, 2021).
Chorea (2 papers, 2022 to 2024). Chorea (Greek for 'dance') refers to widespread arrhythmic involuntary movements of a forcible, jerky and restless fashion. "The literature identified conditions linked to variants of the NKX2-1, SLC16A2, and ATM genes as causes of the chorea phenotype associated with multisystem impairment." (PMID 38921008, 2024).
gastric cancer (1 paper, 2025). A primary or metastatic malignant neoplasm involving the stomach. "On the other hand, abnormal methylation of genes, for example, IGF2, SLC16A2, SOX11, P2RX7, and MYOD1, were identified in H. pylori infection and significantly correlated with gastric cancer and its clinicopathological features." (PMID 41614769, 2025).
generalized dystonia (1 paper, 2022). "In eight patients with generalized dystonia from infancy, the mutation of PIGA, TCF4, CHRNG, SLC16A2, KCNQ2, NACC1, CTNNB1, or ARSA gene were found to be causative." (PMID 35719373, 2022).
goiter (1 paper, 2021). Enlargement of the thyroid gland usually caused by lack of iodine in the diet, hyperthyroidism, or thyroid nodules. "Patients with SLC16A2 mutations exhibit psychomotor deficits associated with Allan–Herndon–Dudley syndrome (AHDS), with rare cases also exhibiting goiter, while no apparent brain development and neurological defects have been observed in Slc16a2 mutant mice." (PMID 34440752, 2021).
pancreatic cancer (1 paper, 2020). "The boxplot of the RNA-Seq expression in 179 pancreatic cancer vs 171 normal pancreas samples demonstrated that SLC16A1, SLC16A2, SLC16A3, SLC16A4, SLC16A5 and SLC16A13 were increased with statistical meaning." (PMID 32355273, 2020).
selenium deficiency (1 paper, 2021). A nutritional deficiency disease resulting from inadequate selenium levels in the body, which can lead to impaired function of selenoproteins essential for antioxidant defense and thyroid hormone metabolism. "The mRNA abundance of thyroid receptor alpha (Thra), thyroid receptor beta (Thrb), and monocarboxylate transporter 8 (Slc16a2) was not altered by maternal selenium deficiency." (PMID 33769708, 2021).
Sepsis (1 paper, 2017). Sepsis is defined as life-threatening organ dysfunction caused by a dysregulated host response to infection. "In contrast, CLP-induced sepsis promoted a 53% decrease in liver Slc16a10 mRNA expression (P < 0.01) and a 49% decrease in liver Slc16a2 mRNA expression (P < 0.05)." (PMID 29118715, 2017). "In CLP-induced sepsis, Slc16a2 mRNA expression decreased 48% compared to control (P < 0.05)." (PMID 29118715, 2017). "Herein, we aimed to evaluate the central and peripheral expression of genes involved in the transport (MCT8/Slc16a2 and MCT10/Slc16a10), metabolism (Dio1, Dio2, and Dio3) and action (Thra and Thrb) of TH during NTIS induced by fasting or sepsis." (PMID 29118715, 2017). "In the total hypothalamus, the expression of Slc16a2, Slc16a10, Dio3, and Thrb did not change in these two models fasting and CLP-induced sepsis." (PMID 29118715, 2017).
viral infection (1 paper, 2022). "SLC-mediated transporters for thyroid hormone, ions, amino acids, choline, and energetic substrates (e.g., SLC16A2, SLC41A3, SLC16A10, SLC44A1, and SLC35C2) were downregulated following viral infection." (PMID 36314791, 2022).
tumor (5 papers, 2013 to 2023). "Then, we found that the protein expression of SLC16A2 was higher in BC tumor tissues, whereas that of BTG1 was higher in adjacent normal tissues by immunohistochemical staining assay." (PMID 36998462, 2023).
cancer (4 papers, 2020 to 2023). A tumor composed of atypical neoplastic, often pleomorphic cells that invade other tissues. "We investigated the single nucleotide variations (SNVs) of HFRS genes in different cancers and observed that some genes (CCT6A, TF, KRT14, P4HA2, PGK1, SLC16A2, and STC2) were frequently mutated in COAD, STAD, UCEC, and SKCM." (PMID 36998462, 2023). "SLC16A2 is a member of SLC16 gene family, that encodes monocarboxylate transporters, but its function in cancer has not been identified yet, which required further investigation." (PMID 36998462, 2023).
neurological diseases (4 papers, 2021 to 2025). "It is notable that mutations in the gene for MCT8 (SLC16A2) result in impairment of TH passage through the blood–brain barrier and are associated with severe neurological diseases (i.e., Allan–Herndon–Dudley syndrome)." (PMID 34885918, 2021).
neurodegenerative disease (1 paper, 2022). A disorder of the central nervous system characterized by gradual and progressive loss of neural tissue and neurologic function.
SLC16A2 also shares sentences with these, for which no sentence is quoted: hyperthyroidism (17 papers); Cognitive impairment (6); neurodevelopmental disorder (6); thyrotoxicosis (6); Anxiety (4); cerebral palsy (4); congenital hypothyroidism (4); Central hypothyroidism (3); intrauterine growth restriction (3); movement disorder (3); Obesity (3); demyelinating disease (2); genetic disorder (2); Huntington disease (2); hyperthyroxinemia (2); Neurodevelopmental delay (2); Alzheimer disease (1); aspiration pneumonia (1); Ataxia (1); atherosclerosis (1); autism (1); Autoimmunity (1); Brain atrophy (1); breast carcinoma (1); Cachexia (1); cardiac arrhythmia (1); cryptorchidism (1); deficiencies (1); diabetic cardiomyopathy (1); Dyskinesia (1).
A further 30 diseases each share a sentence with SLC16A2 in 1 paper.